CXCL1 (C-X-C motif chemokine ligand 1)
Diseases named in the same sentence as CXCL1 in open-access papers (continued):
Sharing a sentence is not in itself a finding about the gene and the disease.
tumor (continued). "Accumulating evidence indicates that inflammatory mediators-including CCL2, CCL3, CCL5, CXCL1, CCL20, TNF-α, IL-6, IL-8, and TGF-β-contribute to tumor growth, metastasis, immune modulation, and therapeutic resistance." (PMID 42245673, 2026). "To evaluate the importance of CXCL1/2 and CFB in driving NET formation under treatments, we applied Dox in combination with SB225002 or LNP023, the inhibitors of CXCR2 (the co-receptor of CXCL1/2) or CFB, respectively, in orthotopic 4T1 and MCF-7 tumor model." (PMID 41480760, 2026). "As expected, pretreatment of human peripheral monocyte-derived macrophages with UNC2250 decreased tumor cell debris–induced elevation of CXCL1/2 and CFB, suggesting that increased engulfment of tumor debris promoted CXCL1/2 and CFB production." (PMID 41480760, 2026). "Mechanistically, macrophage-engulfed cathepsin C (CTSC) from tumor debris activates TLR4/NF-κB signaling, upregulating CXCL1/2 and complement factor B (CFB) to drive neutrophil recruitment and NET formation." (PMID 41480760, 2026). "TANs are neutrophils recruited to tumor sites via chemokines (including CXCL1, CXCL2, and IL-8) secreted by tumor cells and stromal cells." (PMID 40771826, 2025). "Our findings are consistent with these results, as G31P inhibited CXCL1, CXCL2 and TNF-α in tumor and bleomycin-induced lung tissues, alongside decreased MPO activity and F4/80+ macrophage infiltration." (PMID 41425704, 2025). "In a murine lymphoma model, ILC2s were able to produce a large amount of the CXCR2 ligands CXCL1 and CXCL2, and interaction with a CXCR2-expressing tumor was shown to induce massive tumor-specific apoptosis in a CXCR2-specific way." (PMID 39858045, 2025). "CXCL1, CXCL5 and CXCL8 can recruit neutrophils and MDSCs and contribute to immune suppression and can also promote tumor cell migration and invasion of some tumor types." (PMID 40176808, 2025). "Adipocyte-derived IL6 activates STAT3/NF-κB pathway in TNBC cells to promote the expression and secretion of CXCL1 in TNBC and promote tumor progression." (PMID 40841364, 2025). "Mechanistic studies suggest that CXCL1 directly binds to the SOX4 promoter, activating its transcription via NF-κB signaling, ultimately promoting tumor progression and metastasis." (PMID 40330466, 2025). "The cluster 6 monocytes were defined by high expression of multiple pro-tumor genes (IL1B, SERPINB2, CCL2, CXCL1, CXCL5, CXCL8, CCL3, CCL20)." (PMID 40176808, 2025). "They further confirmed that paclitaxel treatment led to the release of CXCL1-enriched EVs from apoptotic TNBC cells (EV-Apo), which were taken up by macrophages, promoting their polarization to the M2 phenotype and enhancing tumor chemoresistance and invasion." (PMID 40103824, 2025). "The CXCL1/8-CXCR1/2 axis mediates the progression of multiple tumors, and high levels of CXCL1 and CXCL8 in tumors have been shown to be correlated with tumor burden and poor prognosis." (PMID 40148310, 2025). "IL‐1β also promotes MDSC differentiation by triggering the secretion of chemokines like CXCL1 and CXCL2, which attract MDSCs to the tumor site, thus reinforcing the tumor‐promoting functions within the TME." (PMID 39558859, 2025). "Network analysis highlighted immune-related hub genes (CXCL1, CCL20, IL12B, and STAT4) involved in chemotaxis, leukocyte migration, and cytokine signaling, linking immune dysregulation to tumor development." (PMID 40445003, 2025). "Meanwhile, the YUMM1.7 model was more sensitive to chemotherapeutic treatment, secreted higher levels of chemokines CCL2, CXCL1, and CX3CL1, and showed higher infiltration of lymphocyte and myeloid subsets at the same tumor size." (PMID 40878826, 2025). "This was demonstrated in a recent study in which the reduced expression of CXCL1 and suppression of PMN-MSDC led to the inhibition of tumor growth in a mouse model." (PMID 40310432, 2025).
tumor (continued). "Neutrophils contribute to the establishment of pre-metastatic niches by secreting chemokines such as ARG1, CXCL1, CXCL2, CXCL10, CCL2, CXCR2, and vascular endothelial growth factor A (VEGFA), which attract tumor cells to metastatic sites." (PMID 40227814, 2025). "For instance, the IL-17B/IL-17RB axis activates the expression of chemokines such as CCL20, CXCL1, IL-8, and TFF1 via the ERK1/2 signaling pathway, which in turn influences tumor metastasis and the recruitment of macrophages and endothelial cells." (PMID 40948749, 2025). "CXCL1 and CXCL2 sustain chronic inflammation and facilitate tumor development by interacting with the CXCR2 receptor." (PMID 40430079, 2025). "Across multiple preclinical tumor models, RT has been shown to increase the expression of cytokines such as IL-1β, GM-CSF (CSF2), and G-CSF (CSF3), along with chemokines including CXCL1, CXCL2, CXCL5, CCL2, and CCL5." (PMID 40805288, 2025). "A number of ligands, including CXCL1, CXCL2, CXCL5, and CXCL8, converge on CXCR2, thereby coordinating neutrophil recruitment, angiogenesis, epithelial–mesenchymal transition, and tumor proliferation." (PMID 40943634, 2025). "As CSCs acquire enhanced immune evasion capabilities through epigenetic editing, they secrete substantial amounts of factors such as GM-CSF, CXCL1, CXCL2, and CXCL8, which recruit MDSCs to the tumor core." (PMID 41368628, 2025). "Specifically, the CXCL1, IFNG, and SERPINE1 in the tumor group had higher expression, while PIM1 and STK40 in the tumor group had lower expression." (PMID 40455337, 2025). "Whereas, iCAFs were located distantly from the tumor cells and characterized by low α-SMA expression and secretion of inflammatory mediators including IL6, C-X-C motif chemokine ligand 1 (CXCL1), LIF, IL11, and CXCL2." (PMID 40296919, 2025). "In prostate cancer lacking PTEN, activated JAK2/STAT3 signaling established an immunosuppressive tumor microenvironment via SASP factors such as CXCL1, CXCL2, and IL-6 and resulted in tumor growth and chemoresistance." (PMID 40862837, 2025). "CXCL1 and CXCL5 recruit M-MDSCs, mediating immunosuppression by inhibiting CD8+ T cell infiltration, thereby promoting tumor progression." (PMID 40607438, 2025). "Several CAF-derived chemokines such as CCL2, CCL26, IL6, CXCL1, and CXCL8 mediate tumor progression, angiogenesis, and drug resistance, suggesting that tumor–CAF crosstalk is a bidirectional, dynamic, and adaptive process." (PMID 40447617, 2025). "In the tumor microenvironment, macrophage GPR35 promotes VEGF, CXCL-1 and MMPs expression through the NKA-Src signaling axis, thereby driving angiogenesis and matrix remodeling." (PMID 41459506, 2025). "CXCL1 interacts with its receptors CXCR1 or CXCR2 to recruit neutrophils, a process that facilitates their recruitment and activation within the tumor microenvironment and circulation." (PMID 40528159, 2025). "In NSCLC, CXCL1 and 8 are particularly important ELR+ CXC chemokines involved in both tumor progression and drug-induced inflammation." (PMID 41425704, 2025). "This in turn facilitates the recruitment of mesenchymal stem cells mediated by C-X-C motif chemokine ligand 1 (CXCL1), remodels the TME, and accelerates tumor progression." (PMID 40589733, 2025). "This study investigates the role of the C-X-C motif chemokine ligand 1 (CXCL1), secreted by OSCC cells, in promoting CAF differentiation and its downstream impact on tumor progression." (PMID 40490643, 2025). "In contrast, our findings indicate that in osteoblasts, CXCL1 activates the TGF‐β signalling pathway to inhibit apoptosis, suggesting a possible reciprocal relationship between CXCL1 and TGF‐β signalling in osteoblasts and tumour cells." (PMID 41165410, 2025). "For instance, CXCL1 and CXCL12 enhances the tumor’s resistance to radiation through both direct and indirect mechanisms." (PMID 40134607, 2025).
tumor (continued). "NK cells-derived chemokines, such as CCL5, CXCL1, and CXCL2, are crucial for recruiting conventional DC1 (cDC1) to tumor sites and the subsequent activation of T cells." (PMID 41583489, 2025). "A comprehensive analysis of 23 cytokines and chemokines revealed elevated levels of tumor-derived GM-CSF, IFN-γ, MCP-1 and CXCL1, alongside a decrease in IL-6 and Gal-9, further supporting the enhanced T cell activity observed following LDHC knockdown." (PMID 40108668, 2025). "The binding of CXCL1 and CXCR2 can be influenced by the NF-κB pathway, impacting the proliferation and spread of tumor cells." (PMID 40841364, 2025). "Our study revealed a correlation between MMP14 expression and various molecules regulating tumor immune cells, including CSF1R, HAVCR2, KDR, PDCD1LG2, TGFB1, CD70, CD86, and CXCL1." (PMID 40352589, 2025). "For example, tumor-derived conditioned medium containing high levels of CCL2, CXCL1, and CXCL5 inhibits DC maturation in vitro." (PMID 41445742, 2025). "The present study reveals that upon activation in tumor cells, IL7R promotes CXCL1 secretion by facilitating the nuclear translocation of NF-κB, which then binds to the CXCL1 promoter." (PMID 41360767, 2025). "Tumor cells and stromal cells secrete a variety of chemokines and cytokines, including cysteine X cysteine ligands such as CXCL1, CXCL2, CXCL5, and CXCL8 (IL-8), that attract neutrophils to the tumor site." (PMID 40227814, 2025). "C-X-C motif chemokine ligand 1 (CXCL1), a member of the CXC chemokine family, is controlled by multiple signaling cues, including those from the tumor microenvironment." (PMID 40490643, 2025). "In PAs/PitNETs, CXCL1 recruits macrophages and neutrophils, promoting tumor progression, and CCL5 enhances the tumor invasiveness." (PMID 40064752, 2025). "CXCL1, through its receptor CXCR2, induces the activation of Snail, which leads to an epithelial-to-mesenchymal transition (EMT) and the migration of tumor cells." (PMID 40427171, 2025). "CXCL1, CXCL2 and CXCL8 proteins were almost completely removed from the tumours after AEFs treatment." (PMID 39161078, 2025). "The results revealed remarkable increases in the expression levels of the neutrophil chemokines CXCL1 and CXCL2 within the tumor tissues after the intratumoral injection of LPS." (PMID 39799561, 2025). "Numerous studies revealed that chemokines such as CXCL1, CXCL2, IL-8 (CXCL8), CXCL5, CXCL12, CCL2, and MIP-1α (CCL3) promote the infiltration of neutrophil to the tumoural microenvironment." (PMID 40852716, 2025). "One approach is to stop the chemokines such as CXCL1, CXCL2, and CXCL8 (IL-8) that draw neutrophils to the tumor site to prevent their recruitment and usual overexpression in the tumor microenvironment." (PMID 41267750, 2025). "Overexpression of DEC2 in OSCC cells induced dormancy and resistance to cisplatin, while CAF-derived CXCL1 downregulated DEC2, confirmed by qRT-PCR results, leading to the reactivation of dormant cells and contributing to tumor recurrence." (PMID 41404065, 2025). "Previous studies have shown that tumor-derived CCL2 promotes the recruitment of TAMs and MDSCs, while CXCL1 promotes the recruitment of MDSCs." (PMID 41282257, 2025). "CXCL1, known for its chemotactic effect on neutrophils, is promoted by YHJD in liver tissues to induce the chemotaxis of anti-tumor neutrophil infiltration, potentially reducing liver metastasis in CRC patients." (PMID 40083557, 2025). "Doublecortin-like kinase 1 (DCLK1), a biomarker of colorectal CSCs, induces the expression of CXCL1 and CXCL2 through the ERK pathway, facilitating the recruitment of MDSCs into an immunosuppressive TME and promoting tumor growth." (PMID 41368628, 2025). "Combined CB + miR + R/SLN-CSW suppressed IL-17, G-CSF, and CXCL1, increased infiltration of CD4+ and CD8+ T cells, reduced Tregs and M2-TAMs, and inhibited tumor growth in CT-26 bearing mice." (PMID 41304839, 2025).
tumor (continued). "Using next‐generation sequencing, we found that in tumor tissues with high CCL24 expression, iCAF markers (IL1A, IL1B, IL6, CXCL1, and CXCL5) were significantly highly expressed, indicating high infiltration of iCAFs in the TME." (PMID 40397411, 2025). "The macrophagehigh ductal cell type 2 samples showed a higher number of tumor cells expressing the NF-κB target genes TNFAIP3 and CXCL1 compared to macrophagelow samples, consistent with the known role of TNF in activating NF-κB signaling in PDAC." (PMID 40634284, 2025). "Besides, CXCL1 could shape the tumor microenvironment to affect chemoresistance." (PMID 39394189, 2024). "The present study provides evidence that CXCL1 secreted by cancer cells stimulates macrophages to secrete EGF, which contributes to tumor cell invasion and metastasis via EGFR in OSCC cells." (PMID 38713320, 2024). "CXCL1, along with other CXCR2 ligands in bladder cancer tumors, is responsible for recruiting neutrophils into the tumor niche." (PMID 38673949, 2024). "The results of tumor transcription spectroscopy showed that viral infection caused the increase of neutrophil chemokine 1(C-X-C ligand 1, CXCL1) and chemokine 5(C-X-C ligand 1, CXCL5), and induced neutrophil infiltration into infected tumor tissues." (PMID 39697335, 2024). "Upon tumor cell activation, a large number of CXCL5, CXCL3, CSF3, CCL20, and CXCL1 are expressed to recruit neutrophils." (PMID 38167055, 2024). "The immune genes CXCL1, CXCL2, IL1B, IL6, CXCL8, PTGS2, and SPP1 demonstrated elevated expression levels in tumor tissue (TU) relative to all other tissues, thus validating the results obtained from the NanoString analysis (Supplementary 1)." (PMID 38979413, 2024). "The study revealed that CA-MSCs highly express CXCR1/2 ligands such as CXCL1, CXCL2, and IL-8, which promote monocyte differentiation towards a pro-tumor M2 phenotype, facilitating tumor progression and the acquisition of chemotherapy resistance." (PMID 38779660, 2024). "Our study emphasized the role of IL6high CAF on tumor cells for elevating level of various cytokine genes including IL6, IL32, IL33, CXCL1, CXCL3 and CXCL8, and oncogenic pathways, such as the Wnt and VEGF signaling pathways." (PMID 38892065, 2024). "In BC, OSM produced by myeloid cells, including TAMs, activates OSMR on CAFs, inducing secretion of chemokines such as CXCL1 and CXCL16, which attract more TAMs to the tumor site, reinforcing a pro-inflammatory feedback loop that facilitates lung metastasis." (PMID 39286635, 2024). "CCL5, CXCL1, CXCL2, CXCL5, and CXCL12 are chemokines produced by senescent cells that have opposite effects on tumor development." (PMID 39007138, 2024). "Studies have shown that tumor necrosis factor-α activated CXCR2 ligands (CXCL1, CXCL2 and CXCL5) expressed by MSCs can effectively aggregate and migrate CXCR2+ neutrophils into tumor and significantly promote tumor metastasis." (PMID 39679363, 2024). "In this study, mice were administered metronidazole, which improved the course of intestinal inflammation and also reduced tumor size and the levels of Ki-67, VEGF and CXCL1 proteins." (PMID 39518144, 2024). "The downregulation of SLC7A2 upregulated CXCL1 through the PI3K/Akt/NF-κB pathway, recruiting bone marrow-derived suppressor cells and exerted a tumor immune inhibitory effect." (PMID 38287304, 2024). "Consistently, under the stimulation of heat-killed P. intermedia in our study, the glutamatergic system was downregulated, while the expression levels of CXCL1, CXCL2, and CXCR2 increased and Tregs accumulated in tumor tissues, resulting in tumor progression." (PMID 38515216, 2024). "CXCL1, belonging to the CXC chemokine family, has been documented as a pivotal factor in the development of inflammatory diseases and various tumor progression." (PMID 39287311, 2024).
tumor (continued). "The overexpression of CXCL1 and GM-CSF via the PI3K-AKT pathway and the recruitment and reprogramming of neutrophils suppress the cytotoxicity of CD8+ T cells, promoting tumor progression." (PMID 38982491, 2024). "In the present study, we investigated the correlation between the expression of CXCL1 in HCC tissue samples and the tumor stage." (PMID 39132161, 2024). "As verified by exocytotic chemokines, the expression of tumor-promoting chemokines, including CCL3, CCL5, CCL7, CCL11, CXCL1, and CXCL12, showed a downward trend after MWA." (PMID 38779358, 2024). "NF-κB plays an important role in CAFs, mediating the upregulation of proteases such as COX2, CXCL1, CXCL2, CYR61/CCN1, IL-1β, IL-6, and osteopontin, thus promote tumor growth, recruit macrophages, and form tumor vasculature." (PMID 39146202, 2024). "Recruitment and education of Gr1+CD11b+ cells in the TME, particularly through the chemokines CCL2, CXCL1, and CXCL2 or IL-33, are considered critical steps for their contribution to tumor progression and metastasis." (PMID 38236642, 2024). "ACKR1 on the surface of endothelial cells binds, clears and regulates various chemokines such as CXCL1, CXCL2, CCL13 and CCL18, which play key roles in angiogenesis and tumour progression." (PMID 39601163, 2024). "Mechanistically, P. anaerobius administration activated integrin α2β1–NF-κB signalling in CRC cells to induce secretion of CXCL1 and recruit CXCR2+ MDSCs into tumours." (PMID 38750176, 2024). "The expression levels of CXCL1, CXCL2, and CXCL8 were significantly elevated, showing a more than threefold increase in over 80% of the analyzed tumor samples." (PMID 38979413, 2024). "CXCL1, upon binding to the CXCR2 receptor, initiates a series of signaling pathways that notably affect tumor growth and migration." (PMID 39044834, 2024). "In immunologically inactive BC, it has been observed that the downregulation of TGF-β in stromal fibroblasts can lead to an upregulation of CXCL1, which then activates STAT3 by acting on CXCR2 in tumor cells." (PMID 39107856, 2024). "Although multiple cell types express CXCL1 in the TME, several studies demonstrate that elevated CXCL1-mediated signaling supports tumor-promoting macrophage differentiation and cancer progression in a macrophage-dependent manner." (PMID 38984891, 2024). "At the same time, extracellular tumor-promoting chemokines, such as CCL3, CCL5, CCL7, CCL11, CXCL1, and CXCL12, were also downregulated." (PMID 38779358, 2024). "In our search for clinically feasible approaches for inhibiting CXCL1 signaling, we utilized reparixin, which has been reported to inhibit TNBC tumor growth and metastasis." (PMID 38393465, 2024). "CXCL1 and CXCL8, members of the angiogenic CXC chemokine family are highly expressed only on the border of annotated tumor regions in our study, suggesting that an immune exclusion and blockage by the tumor." (PMID 38729966, 2024). "CXCL1 and CXCL8 induced tumor cell binding to brain endothelial cells, and endothelial cell tube formation/proliferation." (PMID 38786066, 2024). "In Pten‐null senescent tumours, the JAK2/STAT3 pathway was activated, resulting in the secretion of CXCL1, CXCL2 and IL‐6, thereby promoting macrophage M2 polarisation." (PMID 39270064, 2024). "All genes, except PGLYRP2, were upregulated in tumor tissues, with significant increases found for CAT (P < 0.01), CXCL1 (P < 0.05), and RAF1 (P < 0.05), which agreed with the previous results." (PMID 38806963, 2024). "A substantial body of research substantiates that CC chemokines (e.g., CCL2, CCL5) and CXC chemokines (e.g., CXCL1, CXCL2, CXCL5) recruit diverse immune cells, such as CCR2+ monocytes and CXCR2+ neutrophils, to tumor sites." (PMID 39206194, 2024).